KCNJ2 (potassium inwardly rectifying channel subfamily J member 2)
Diseases named in the same sentence as KCNJ2 in open-access papers (continued):
Sharing a sentence is not in itself a finding about the gene and the disease.
papillary thyroid carcinoma (5 papers, 2014 to 2025). "Kir2.1(KCNJ2) is associated with the development of papillary thyroid carcinoma(PTC), and interference with KCNJ2 inhibits cell proliferation, invasion, migration, and EMT processes." (PMID 36703789, 2022). "Furthermore, inhibition of KCNJ2 has been associated with reduced proliferation, migration, and epithelial-mesenchymal transition (EMT) progression in papillary thyroid carcinoma cells." (PMID 38553531, 2024). "While ENPP3 is involved in tumor cell migration and KCNJ2 is overexpressed in papillary thyroid carcinoma, the role of either of these factors is unknown in RCC." (PMID 24979721, 2014).
Timothy syndrome (5 papers, 2017 to 2024). "These include Andersen–Tawil syndrome (LQT7, KCNJ2) in which skeletal developmental abnormalities are observed; Timothy syndrome (LQT8, CACNA1C) with characteristic neurological, facial and limb features and JLNS syndrome, associated with sensorineural deafness (KCNQ1-KCNE1 genes)." (PMID 35052786, 2022). "Moreover, there are three atypical LQTS or multisystem syndromic disorders including Ankyrin-B syndrome gene ANK2 (LQT4), Anderson–Tawil syndrome (ATS) gene KCNJ2 (LQT7), and Timothy syndrome (TS) gene CACNA1C (LQT8)." (PMID 38666937, 2024).
ventricular tachycardia (5 papers, 2015 to 2025). A disorder characterized by an electrocardiographic finding of three or more consecutive complexes of ventricular origin with a rate greater than a certain threshold (100 or 120 beats per minute are commonly used). "Mutations in the KCNJ2 gene account for only 50% of patients with a classic triad of symptoms: ventricular tachycardia and QTc prolongation, characteristic craniofacial abnormalities, and periodic skeletal muscular weakness." (PMID 35456365, 2022). "R218W,KCNJ2-p.R67W and KCNJ2-p.R218Q, finding abnormal Ca2+release and ventricular tachycardia." (PMID 40351699, 2025).
gastric cancer (4 papers, 2021 to 2025). A primary or metastatic malignant neoplasm involving the stomach. "KCNJ2 can bind to and activate serine/threonine kinase 38, thereby promoting the invasion of gastric cancer cells." (PMID 36864422, 2023).
ventricular fibrillation (4 papers, 2015 to 2024). A disorder characterized by an electrocardiographic finding of a rapid grossly irregular ventricular rhythm with marked variability in QRS cycle length, morphology, and amplitude. "We confirmed the SQT3 caused by the KCNJ2 E299V mutation can cause sudden cardiac death during ventricular fibrillation through the electromechanical simulation." (PMID 32328155, 2020). "Therefore, we investigated the electrophysiological changes and the concomitant mechanical responses according to the expression levels of the KCNJ2 E299V mutation during sinus rhythm and ventricular fibrillation." (PMID 32328155, 2020). "So far, there were no cases of ventricular tachycardia or ventricular fibrillation observed in patients with KCNJ2 E299V mutations, but it was reported that the E299V mutation may induce ventricular arrhythmia." (PMID 32328155, 2020).
asthma (3 papers, 2017 to 2026). "Genome-wide association studies have shown that several SNPs of KCNJ2, a member of the inwardly rectifying potassium channel family, are associated with asthma in patients." (PMID 41960844, 2026). "From the analysis of GEO database, expression of KCNJ2 is decreased in patients with severe asthma, suggesting its expression may be associated with mechanisms of airway remodeling driving by epithelial dysfunction." (PMID 29137293, 2017). "The results showed that KCNJ2 expression was significantly downregulated in patients with severe asthma." (PMID 29137293, 2017). "In conclusion, our study shows that aberrant regulations of mir-203a to MEF2C and mir-3065-3p to MDGA1, as well as downregulation of KCNJ2, play important roles in airway epithelial homeostasis in asthma." (PMID 29137293, 2017). "We proposed that aberrant regulations of mir-203a-MEF2C and mir-3065-3p-MDGA1, as well as downregulation of KCNJ2, play important roles in airway epithelial homeostasis in asthma." (PMID 29137293, 2017). "We also found that KCNJ2, a potassium channel, was downregulated in severe asthma and may promote epithelial cell apoptosis." (PMID 29137293, 2017). "However, the role of KCNJ2 in airway inflammation and remodeling in asthma remains unknown." (PMID 41960844, 2026).
autism spectrum disorder (3 papers, 2018 to 2024). A spectrum of developmental disorders that includes autism, and Asperger syndrome. "Recently, a role of Kir channels was reported in autism spectrum disorders (ASDs) due to the identification of two mutations (p.Arg18Gln and p.Val84Met) in the hKCNJ10 gene coding for the Kir4.1 subunit as well as one mutation in the KCNJ2 gene (p.Lys346Thr) coding the Kir2.1 subunit." (PMID 29615871, 2018).
cardiac hypertrophy (3 papers, 2017 to 2020). "Previous studies have confirmed that miR‐195 expression is increased in cardiac hypertrophy, and the bioinformatics website predicted by Targetscan software shows that miR‐195 can directly target CACNB1, KCNJ2 and KCND3 to regulate Cavβ1, Kir2.1 and Kv4.3 proteins expression." (PMID 32468736, 2020).
osteosarcoma (3 papers, 2023 to 2025). A usually aggressive malignant bone-forming mesenchymal neoplasm, predominantly affecting adolescents and young adults. "For example, KCNJ2 has been implicated in promoting epithelial–mesenchymal transition and metastasis in osteosarcoma." (PMID 40314029, 2025). "For instance, the interaction between KCNJ2 and the HIF1α transcription factor has been shown to establish a positive-feedback loop, contributing to osteosarcoma metastasis." (PMID 38553531, 2024). "Additionally, in osteosarcoma, KCNJ2 overexpression correlates with advanced disease and poor patient outcomes, as it enhances metastasis by forming a positive feedback loop with HIF-1α." (PMID 40314029, 2025).
scoliosis (3 papers, 2013 to 2025). A congenital or acquired spinal deformity characterized by lateral curvature of the spine. "FBN1, FBN2, and variants near SOX9, and KCNJ2 are associated with severe scoliosis (greater than 40 degrees)." (PMID 39781499, 2025). "rs12946942 is on chromosome 17q24.3 near the genes SOX9 and KCNJ2, which when mutated cause scoliosis phenotypes." (PMID 24023777, 2013).
Cognitive impairment (2 papers, 2019 to 2021). Abnormal cognition is characterized by deficits in thinking, reasoning, or remembering. "Mild-to-severe cognitive impairment (MMSE) was found to be more likely in the presence of the KCNJ2-rs236514 variant (A) allele in this elderly Australian cohort." (PMID 33668367, 2021). "Our results suggest that the KCNJ2-rs236514 variant allele may have a role in the cognitive impairment that characterizes these conditions, particularly in light of the SNP’s demonstrated impact on sour taste." (PMID 33668367, 2021). "This cross-sectional analysis used scores from the Mini-Mental State Examination (MMSE) as an index for cognitive impairment and assessed the relationship between this index and the common sour-taste SNP, KCNJ2-rs236514, and three diet-quality indices." (PMID 33668367, 2021). "In the absence of directly comparable research, results are contextualized by related studies on the KCNJ2 gene, rs236514 SNP, and the structural and biological commonalities in taste, the brain, and cognitive impairment." (PMID 33668367, 2021). "Therefore, the possible relationship between KCNJ2-rs236514 sour genotype, diet quality, and a marker of cognitive impairment was assessed in a well-characterized elderly cohort." (PMID 33668367, 2021). "Among the significantly enriched signaling pathways from KEGG analysis, oxytocin signaling pathway (PATH:04921; Cacng2, Adcy1, Kcnj4, Kcnj9, Adcy8, Pik3cd, Elk1, Adcy4, Camkk2, Cacng7, Nos3, Kcnj2) may play an important role in the sevoflurane-induced cognitive impairment." (PMID 31582589, 2019).
HyperPP (2 papers, 2020 to 2021). "In humans, genetic confirmation of known pathogenic variants in SCN4A-related PMC and HyperPP, and KCNJ2-related Andersen–Tawil syndrome-related, is included in the diagnosis of these disorders." (PMID 34828398, 2021). "Likewise, in human medicine, patients with phenotypical characteristics of PMC, HyperPP, and Andersen–Tawil syndrome were found not to present pathogenic variants in the SCN4A or in KCNJ2, suggesting further genetic heterogeneity." (PMID 34828398, 2021).
interstitial lung disease (2 papers, 2020 to 2025). A diverse group of lung diseases that affect the lung parenchyma. "The cutoff KCNJ2 level of 1.795 ng/mL exhibited an 81.48% specificity and a 72.62% sensitivity for distinguishing between the patients with IPF and those with other interstitial lung diseases." (PMID 32184906, 2020). "In this study, we demonstrated that KCNJ2 gene and protein expression was significantly increased in fibroblasts and BAL fluids, respectively, from patients with IPF compared with NCs and patients with other interstitial lung diseases." (PMID 32184906, 2020).
myopia (2 papers, 2019 to 2022). "Validation of the role of KCNMA1 in myopia progression is needed, particularly in ion channel activity which is one of the major functional pathways implicated, with an existing pool of several associated genes (KCNQ5, KCNJ2, and CACNA1D)." (PMID 31415580, 2019).
paroxysmal AF (2 papers, 2017 to 2022). "Missense mutations in KCNJ2 were also reported in human patients with paroxysmal AF." (PMID 36187798, 2022).
sarcoidosis (2 papers, 2020 to 2022). Sarcoidosis is a multisystemic disorder of unknown cause characterized by the formation of immune granulomas in involved organs. "ROC curves showed a clear difference between the IPF patients and those with NSIP, HP, or sarcoidosis at a cutoff KCNJ2 protein level of 1.795 ng/mL." (PMID 32184906, 2020). "Interestingly, KCNJ2, one of the identified cross-tissue signature genes, is included as a predictor, which is activated in IPF but lacks exploration in sarcoidosis." (PMID 36203777, 2022).
acute monocytic leukemia (1 paper, 2016). Acute monoblastic leukemia (AML-M5), is one of the most common subtypes of acute myeloid leukemia (AML) that is either comprised of more than 80% of monoblasts (AML-M5a) or 30-80% monoblasts with (pro)monocytic differentiation (AML-M5b). "The expression and function of the inward rectifier potassium channel (Kir2.1, KCNJ2) in Human acute monocytic leukemia cell line (THP‐1) cells and human monocytes derived macrophages (HMDMs) were investigated using RT‐PCR and western blotting, and patch clamp technique." (PMID 26689595, 2016).
Anonychia (1 paper, 2020). Aplasia of the nail. "Fortunately, our three patients provide strong evidence that 17q24.3 duplications related to regulatory elements of SOX9 as well as KCNJ2 coding region are a genetic cause of brachydactyly‐anonychia." (PMID 32583964, 2020).
cardiac arrest (1 paper, 2020). Cessation of breathing and/or cardiac function. "We concluded that in both sinus rhythm and fibrillation, the KCNJ2 E299V mutation results in very low contractility regardless of the expression level of mutation and increases the risk of cardiac arrest and cardiac death." (PMID 32328155, 2020).
cognition (1 paper, 2021). Intellectual or mental process whereby an organism becomes aware of or obtains knowledge. "The singular study available on sour taste and the KCNJ2-rs236514 SNP did not analyze data by sex, and neither did the studies demonstrating decreased sensitivity to sour perception in cognition-related diseases." (PMID 33668367, 2021).
cognitive decline (1 paper, 2021). "KCNJ2 genes are highly expressed in the same areas of the brain (cerebral cortex, amygdala, thalamus, hippocampus, and basal ganglia) that demonstrate changes in cognitive decline." (PMID 33668367, 2021).
co‐infection (1 paper, 2020). "Further co‐infection experiments in vitro and in vivo revealed that miR‐26 could partially reverse the up‐regulation of KCNJ2 caused by TCONS‐00106987 overexpression." (PMID 32954646, 2020).
Generalized hypertrichosis (1 paper, 2024). Generalized excessive, abnormal hairiness. "Interestingly, in the literature there are a series of microdeletions centromeric to KCNJ2/KCNJ16 that have been identified in individuals with congenital generalized hypertrichosis with or without gingival hyperplasia (microdeletion 17q24.2-q24.3 syndrome; MIM 135400)." (PMID 39257002, 2024).
gingival hyperplasia (1 paper, 2024). "More broadly, we argue that KCNJ2/KCNJ16 misregulation likely represents the common underlying mechanism in several previously reported patients with gingival hyperplasia and/or hypertrichosis, who harbor deletions and other rearrangements of the 17q24.2-q24.3 region (MIM 135400)." (PMID 39257002, 2024). "In addition, we highlight a previously overlooked potential role for misregulation of the KCNJ2/KCNJ16 genes in the pathomechanism of gingival hyperplasia associated with deletions and other rearrangements of the 17q24.2-q24.3 region (MIM 135400)." (PMID 39257002, 2024). "As a whole, the deepC prediction supports our hypothesis and suggests that the most probable pathogenic mechanism underlying the severe skeletal malocclusion and gingival hyperplasia involves KCNJ2/KCNJ16 misregulation induced by neo-TAD formation and adopted craniofacial enhancers." (PMID 39257002, 2024). "In line with this, there are at least two instances of complex SV with BPs near the KCNJ2/KCNJ16 genes that potentially modify their regulatory landscape in individuals with syndromic gingival hyperplasia." (PMID 39257002, 2024). "Altogether, a misregulation of the potassium channel KCNJ2/KCNJ16 genes seems likely to contribute to the gingival hyperplasia." (PMID 39257002, 2024).
idiopathic scoliosis (1 paper, 2023). A scoliosis with no known cause. "Moreover, a mutation in 17q24.3-rs12946942 near the KCNJ2 may be associated with the phenotypes of adolescent idiopathic scoliosis." (PMID 37683138, 2023).
lung carcinoma (1 paper, 2023). "Kir channel subfamily J member 2 (KCNJ2 or Kir2.1) and Kir channel subfamily J member 4 (KCNJ4 or Kir2.3) have been involved in lung cancer." (PMID 37408210, 2023).
oral cancer (1 paper, 2017). "Inhibition of KCNJ2 can increase the cisplatin-induced apoptosis in oral cancer." (PMID 29137293, 2017).
prostate carcinoma (1 paper, 2024). A carcinoma that arises from epithelial cells of the prostate gland. "In prostate cancer cells, KCNJ2 promotes proliferation by binding to the RELA protein in the nucleus, thereby activating the NF-κB signaling pathway." (PMID 38553531, 2024).
prostate tumor (1 paper, 2013). "Although the nearest protein-coding regions, KCNJ2 and SOX9, are ∼1Mb away, SOX9 is involved in prostate epithelial differentiation and observed to promote prostate tumor cell proliferation when upregulated." (PMID 23593118, 2013).
sarcopenia (1 paper, 2024). Progressive decline in muscle mass due to aging which results in decreased functional capacity of muscles. "Consistently across the three outcomes, RXRA, MDM1, RBL2, KCNJ2, and ADHFE1 were identified as risk factors, while NMB, TECPR2, MGAT3, ECHDC2, and GINM1 were identified as protective factors, all with potential as biomarkers for sarcopenia progression." (PMID 39409102, 2024).
Stillbirth (1 paper, 2023). Death of the fetus in utero after at least 22 weeks of gestation. "Notably, despite previous reports suggesting that variants in ‘sudden death’ genes contribute to unexplained stillbirths, we identified only one inherited candidate variant (VUS) in KCNJ2 (PED049) in our cohort, with no definitive diagnoses (LP/P variants) detected in these genes." (PMID 36658419, 2023).
sudden cardiac arrest (1 paper, 2021). Unexpected rapid natural death due to cardiovascular collapse within one hour of initial symptoms. "In addition, VA reported in patients with KCNJ2 mutations have been described as milder than in RYR2 mutated patient, especially rarely leading to syncope or sudden cardiac arrest." (PMID 34899860, 2021).
thyroid carcinoma (1 paper, 2025). "In thyroid carcinoma, KCNJ2 inhibits proliferation, migration, and EMT progression of papillary cells by upregulating GNG2 expression." (PMID 40314029, 2025).
thyrotoxic periodic paralysis (1 paper, 2022). Thyrotoxic periodic paralysis (TPP) is a rare neurological disease characterized by recurrent episodes of paralysis and hypokalemia during a thyrotoxic state. "In addition, mutations in KCNJ2 have been found associated with non-familial HOKPP, and with thyrotoxic periodic paralysis in humans." (PMID 35158718, 2022).